RETN (resistin)
Diseases named in the same sentence as RETN in open-access papers (continued):
Sharing a sentence is not in itself a finding about the gene and the disease.
Hepatic steatosis (32 papers, 2010 to 2025). Steatosis is a term used to denote lipid accumulation within hepatocytes. "Numerous reports have shown that resistin in adipocyte EVs is strongly associated with hepatic steatosis and other fatty liver diseases." (PMID 38169960, 2023). "In general, melatonin caused a reduction in the traffic of the exosomal resistin generated by adipocytes to hepatocytes, causing greater relief of stress-induced liver steatosis in the ER." (PMID 34177952, 2021). "A previous study showed that loss of resistin prevented hepatic steatosis is related to leptin deficiency." (PMID 25922835, 2015). "In addition to resistin from A-EVs causing liver steatosis through ER stress, ER stress-induced A-EVs can induce NASH." (PMID 36032078, 2022). "Moreover, a positive association between hepatic resistin mRNA levels and hepatic steatosis, inflammation, or fibrosis was reported in several studies." (PMID 36009862, 2022). "Melatonin decreased traffic volume of adipocyte-generated exosomal resistin from adipocytes to hepatocytes, which further alleviated ER stress-induced hepatic steatosis." (PMID 40129979, 2025). "Eventually, Exosome-Melatonin co-treatment alleviates ER-stress-induced hepatic steatosis through a significant downregulation in the expression of adipocyte-derived exosomal resistin." (PMID 39144666, 2024). "In mice, the intraperitoneal administration of SW20.1 reduced body weight, white adipocyte weight in different regions, serum cholesterol levels, adipogenesis-related gene expression, hepatic steatosis, and serum resistin levels." (PMID 37371606, 2023). "Statistically significant positive correlations between hepatic steatosis and resistin concentration in saliva were also found (p = 0.008; r = 0.27)." (PMID 36769216, 2023). "Elevated resistin levels exacerbate mitochondrial damage and hepatic steatosis through the AMP-activated protein kinase (AMPK)/PPARγ coactivator 1α signaling pathway." (PMID 37371606, 2023). "A downregulation of adipokines, including resistin and leptin, involved in the progression of hepatic steatosis was observed after the administration of CT-1 recombinant protein." (PMID 37048824, 2023). "ADe significantly controlled body weight; alleviated hepatic steatosis and adipocyte hypertrophy; reduced aspartate aminotransferase, total cholesterol, insulin, and resistin; and increased adiponectin levels in HFD-fed mice serum." (PMID 36839230, 2023). "In short, melatonin reduced the flow of extracellular resistin from adipocytes to hepatocytes, which further alleviated hepatic steatosis induced by ER stress." (PMID 36032078, 2022). "Together with increased lipid content associated overexpression of resistin and SREBP-1c in HFD mice, this study demonstrated that resistin promotes hepatic lipogenesis and hepatic steatosis through, at least in part, upregulating SREBP-1c." (PMID 25922835, 2015). "EA reduced serum resistin levels and improved hepatic steatosis and serum lipid profile in high-fat fed obese diabetic KK-Ay mice." (PMID 26442119, 2015). "The variability in findings may imply that increased resistin levels are correlated more significantly with heightened tissue resistance to insulin, thereby elevating the likelihood of hepatic steatosis." (PMID 38732626, 2024). "Resistin is an adipocytokine that may aggravate hepatic steatosis via stimulating hepatic ER stress." (PMID 39144666, 2024). "They later demonstrated that resistin was a fundamental cytokine to suppress phosphorylation of protein kinase α activated by 5 ‘adenosine monophosphate, capable of triggering stress in the endoplasmic reticulum, which resulted in hepatic steatosis." (PMID 34177952, 2021). "Additionally, in mice studies resistin induces hepatic steatosis by diminishing mitochondrial content and downregulating mitochondria, leading to changed mitochondrial morphology and impaired mitochondrial function." (PMID 33142854, 2020).
Hepatic steatosis (continued). "Hepatic fat deposition was also reduced by exogenous GH levels, as was the expression of adipocyte-derived adipokines (adiponectin, leptin and resistin), which might improve lipid metabolism and hepatic steatosis." (PMID 20653983, 2010). "The adipokine resistin triggers liver steatosis by inducing ERS, while melatonin counteracted this effect by decreasing resistin delivery via adipocyte-derived exosomes." (PMID 40129979, 2025). "Statistically significant, positive correlations between hepatic steatosis and the concentration of MMP-2 (matrix metalloproteinase 2), resistin, and IL-1β in saliva were also found." (PMID 36769216, 2023). "Studies have found that resistin can increase TG levels, which can increase free fatty acid (FFA) levels and also induce hepatic steatosis, thus aggravating abnormal lipid metabolism." (PMID 37710167, 2023). "Melatonin was found to reduce the level of resistin in EVs and alleviate the HFD-induced hepatic steatosis." (PMID 35770186, 2022). "Circulating resistin levels were positively correlated with hepatic steatosis, portal inflammation, and NAFLD ACTIVITY SCORES in non-diabetic NAFLD patients." (PMID 36009862, 2022). "Indeed, lower serum adiponectin and resistin concentrations and higher serum RBP4 concentrations were evident in children with advanced liver steatosis." (PMID 32718097, 2020). "This meant resistin-enriched EVs might trigger hepatic steatosis without eliciting hepatic inflammation." (PMID 35770186, 2022). "In addition, ob/ob mice and diet-induced obese mice, both lacking resistin, had reduced hepatic steatosis, since the expression of genes involved in hepatic lipogenesis and the secretion of very-low-density lipoprotein (VLDL) were decreased." (PMID 36009862, 2022). "In addition, the same authors indicated that adiponectin, resistin and RBP4 levels could be useful for differentiating patients with advanced liver steatosis from those with mild steatosis." (PMID 32718097, 2020). "EA supplementation also improved hepatic steatosis by reducing triglycerides, which play key role in liver steatosis and ameliorated serum HDLC and non-HDLC levels which might be caused by reduced serum resistin levels." (PMID 26442119, 2015).
Abdominal obesity (29 papers, 2006 to 2025). Excessive fat around the stomach and abdomen. "While the increased TG/HDL-C represented central obesity, which is directly associated with insulin resistant by altering secretion of different adipocytokines namely adiponectin, leptin, resistin and visfatin." (PMID 31640743, 2019). "Moreover, IL-6 and resistin have been associated with abdominal obesity on the one hand and an increased number of senescent T cells on the other hand." (PMID 33922813, 2021). "Our results suggest that extreme central obesity patients have a resistin plateau, or even decrease, relative to other inflammatory signals." (PMID 41011232, 2025). "In abdominal obesity, adipocytes generate numerous adipokines and cytokines, including leptin, adiponectin, resistin, visfatin, and chemerin." (PMID 36922815, 2023). "Our previous research stayed in line with other papers, which revealed that adiponectin levels were inversely correlated with BMI, total body fat, and the markers of abdominal obesity, whereas a positive correlation was observed for leptin and resistin levels." (PMID 37630842, 2023). "PCOS women with abdominal obesity were characterized by lower adiponectin concentrations but also higher leptin and resistin levels." (PMID 37630842, 2023). "It has been demonstrated that resistin correlates inversely with serum HDL cholesterol level in a small group of 34 patients with abdominal obesity." (PMID 28771611, 2017). "In a small group of patients with abdominal obesity HDL cholesterol correlated inversely not only with resistin but also visfatin, and TNF-α." (PMID 28771611, 2017). "Abdominal obesity may affect plasma levels of adiponectin, leptin, cortisol, resistin, insulin, and inflammatory cytokines, such as tumour necrosis factor-α and interleukin-1β, which can enhance neuroinflammation and contribute to depression." (PMID 39487412, 2024). "Furthermore, our study suggests that resistin concentrations are null or weakly correlated with general or abdominal obesity measures, or metabolic and inflammatory biomarkers." (PMID 36428592, 2022). "The comparison of investigated adipokines levels between subjects with and without abdominal obesity revealed significant differences concerning adiponectin and leptin but not resistin levels, both in all-cause dementia and controls." (PMID 28421328, 2017). "The aim of the present study was to investigate the serum levels of selected adipokines (adiponectin, leptin and resistin) in various types of dementia and mild cognitive impairment in relation to abdominal obesity—the most important feature of metabolic syndrome." (PMID 28421328, 2017). "We also did not demonstrate any association of resistin levels with abdominal obesity, neither in all-cause dementia nor in controls, demonstrated after stratification of the data by abdominal obesity, which was confirmed by a Two-way ANOVA analysis." (PMID 28421328, 2017). "In particular, the altered pattern of adipocytokine secretion characterizing central obesity—that is, reduced adiponectin and elevated levels of leptin, resistin, TNFα, and IL-6—increases the production of superoxide anion (O2−), that interferes with NO availability, thus reducing vasodilation." (PMID 20652043, 2010). "The results of our study may suggest that leptin and resistin levels are strongly correlated with abdominal obesity, and their secretion is upregulated in increased abdominal adiposity among PCOS women, whereas hypoadiponectinemia is associated with PCOS diagnosis independently of abdominal obesity." (PMID 37630842, 2023). "Our results showed that serum adipokines, including visfatin, resistin and TNF-α, correlated inversely with serum HDL cholesterol level in patients with abdominal obesity." (PMID 27468698, 2016).
Abdominal obesity (continued). "Adipokines such as leptin, adiponectin, serotonin, resistin and GLP-1, which are secreted by adipocytes or adipose tissues, can result in low-grade inflammation and have important roles in central obesity, IR and T2DM." (PMID 27136447, 2016). "Ferritin and PAI-1 levels positively correlated with waist circumference, while resistin showed a negative correlation with central obesity." (PMID 41011232, 2025). "Additionally, leptin, adiponectin, resistin, TNF-α, IL-6, and other metabolic substances are related to the relationship between abdominal obesity and BMD." (PMID 36313427, 2022). "The level of resistin depended only on dementia status, and not on the presence of abdominal obesity." (PMID 28421328, 2017). "The higher levels of resistin in dementia were stated both in subjects with and without abdominal obesity." (PMID 28421328, 2017). "There was no significant influence of abdominal obesity on resistin levels in the whole dementia group." (PMID 28421328, 2017). "As well,resistin and leptin levels were significantly higher in abdominal obese patientsthan in patients without abdominal obesity or in the control group." (PMID 27627223, 2016). "However, abdominal obesity has not been found to have a significant effect on resistin levels in dementia patients." (PMID 36978817, 2023).
asthma (28 papers, 2011 to 2025). "One study of children showed a protective association between serum resistin concentration and risk for asthma." (PMID 23476106, 2013). "Resistin is associated with different inflammatory states, but there are only a few previous publications on resistin in patients with asthma." (PMID 21615949, 2011). "Moreover, it has been shown that asthma is associated with higher resistin levels and resistin:adiponectin ratios, and that these biomarkers were again higher in asthmatics with more severe disease." (PMID 28696379, 2017). "Although murine data are convincing, it is less clear whether adiponectin, leptin, or resistin plays a role in modulating asthma risk and/or severity in human subjects, although most of the human data are still limited to association studies." (PMID 24288549, 2013). "Moreover, excessive fat accumulation reduces levels of the anti-inflammatory adipokines, adiponectin, omentin-1, and nesfatin-1, while elevating leptin, resistin, and chemerin production, which results in a proinflammatory status associated with asthma development." (PMID 39201554, 2024). "As a consequence, resistin could be a predictor of asthma risk and control." (PMID 34948451, 2021). "Two aberrant signals, annexin and resistin, are found for the DCs of asthma, both of which play a part in inflammatory response." (PMID 41550933, 2025). "S100A8, S100A9, S100A12, and RETN are universally upregulated in various cell types of asthma patients." (PMID 41550933, 2025). "Plasma resistin levels were higher in adults with asthma than in controls, consistent with our findings." (PMID 41550933, 2025). "In expression feature analyses, we observe universal upregulation of S100A8, S100A9, S100A12, and RETN in various cell types of asthma patients, particularly S100A8 and S100A9." (PMID 41550933, 2025). "Although the heterogeneity among asthma cases is prominent, its pathological characteristics converge on the abnormal lymphoid lineage development, the excessive expression of RETN, S100 and ANXA related genes." (PMID 41550933, 2025). "The figure illustrates these findings, confirming RETN as a potential biomarker for childhood asthma." (PMID 41550933, 2025). "Our results show that annexin and resistin are actually two opposite directional signals for the DCs of asthma patients." (PMID 41550933, 2025). "No significant causal relationships were found between leptin, sOB-R, resistin, RBP4, or PAI-1 and sarcoidosis, asthma, COPD, lung cancer, tuberculosis, pneumonia, and sleep apnea syndrome." (PMID 38263093, 2024). "On the other hand, in a cohort of adult patients with asthma, the level of resistin was significantly higher compared to a control group and increased along with the severity of the disease." (PMID 38542187, 2024). "This study found limited evidence supporting a causal relationship between adiponectin, leptin, sOB-R, resistin, RBP4, or PAI-1 and sarcoidosis, asthma, COPD, lung cancer, tuberculosis, pneumonia, or sleep apnea syndrome." (PMID 38263093, 2024). "It is obvious in our work that adiponectin is taking the upper hand in orchestrating asthma pathogenesis than resistin." (PMID 37149591, 2023). "Therefore, resistin may be associated with the phenotype of obese asthma." (PMID 38292857, 2023). "As per a recent study, serum resistin levels were found to be elevated in obese asthmatics especially in females as compared to males which further confirms the role of resistin in the exaggeration of asthma in obese." (PMID 37251328, 2023). "Different studies have analyzed the resistin-mediated mechanisms in obstructive airway diseases, including asthma." (PMID 32630168, 2020). "Other diseases that were proven to have an influence on the resistin concentrations should be excluded (nonalcoholic fatty liver disease, asthma, autoimmune disease, chronic kidney disease)." (PMID 31881807, 2019).
asthma (continued). "Much less data exists addressing a possible relationship between resistin and asthma than that existing for either leptin or adiponectin and asthma." (PMID 24288549, 2013). "Multiple regression analysis revealed that after adjustment for other adiposity measures such as BMI and serum leptin and adiponectin, low serum resistin concentrations were still strongly predictive of asthma." (PMID 24288549, 2013). "Leptin has been reported to be increased or normal in asthma, resistin either increased or decreased, and adiponectin either decreased or normal." (PMID 21615949, 2011). "We present the ELISA results showing that RETN is highly expressed in all 14 asthma cases examined." (PMID 41550933, 2025). "Both annexin and resistin show a self-reinforce trend in the CD14+ monocytes of asthma patients." (PMID 41550933, 2025). "The analyses of cell-cell communication further elucidate the contributory roles of dendritic cells and CD14+ monocytes in the development and heterogeneity of asthma, as they exhibit increased reception and transmission of annexin and resistin signals in the asthma group." (PMID 41550933, 2025). "Furthermore, the resistin–adiponectin ratio reached the highest value in the group of obese men with asthma." (PMID 38542187, 2024). "For that reason, the over-presence of resistin in respiratory epithelium and the over-transcription of MUC encoding genes could be associated to severe asthma, as mucus hypersecretion contributes to airway-obstructive diseases’ pathogenesis." (PMID 32630168, 2020). "Although the role of resistin in asthma pathogenesis is less known, it has been proposed that resistin serum levels and the resistin:adiponectin ratio could be a predictor of asthma risk and lung function in asthma." (PMID 32630168, 2020). "Similarly, other studies have also demonstrated that the level of resistin and resistin/adiponectin ratio are proportionally increased in asthma and are even higher in obese subjects with asthma." (PMID 30050954, 2018). "With the increase in resistin levels, asthma severity is also accordingly increased." (PMID 30050954, 2018). "There are only few publications on resistin in human asthma." (PMID 23476106, 2013). "Studies on animals suggest that resistin and resistin-like molecules may induce inflammation, angiogenesis, and smooth muscle cell proliferation, all processes that are relevant to asthma pathogenesis." (PMID 24288549, 2013). "It seems that another adipokine, resistin, may be also involved in asthma pathogenesis and severity." (PMID 23476106, 2013). "Thus, compared to non-asthma control subjects significant increase in level of IgE (123.1 ± 5.0 vs. 61.1 ± 4.3, p = 0.004), resistin (24.5 ± 1.6 vs. 17.3 ± 1.3, p = 0.001) and IL-4 (18.5 ± 3.6 vs. 9.2 ± 1.4, p = 0.003) pg ml-1." (PMID 23286340, 2013). "Thus IgE, resistin and IL-4 were significantly increased (p 0.004, 0.001 and 0.003, respectively) in children with asthma compared with non-asthma control subjects." (PMID 23286340, 2013). "In particular, this review summarizes basic mechanistic data through population-based and clinical studies addressing the hypothesis that adiponectin, leptin, and possibly resistin may each have a role in asthma." (PMID 24288549, 2013). "In addition, studies have found that asthma is connected with a higher resistin/adiponectin ratio." (PMID 38292857, 2023). "RELMs and resistin may be involved in airway remodeling and asthma progression." (PMID 34948451, 2021). "Therefore, it has been suggested that resistin may be contributing to the obese-asthma phenotype, a possibility reinforced by the fact that reduction in body fat mass also reduces the resistin:adiponectin ratio." (PMID 28696379, 2017). "More recently, it was found that high resistin levels predicted favorable anti-inflammatory effects of inhaled glucocorticoids suggesting that resistin may be a marker of a steroid-sensitive phenotype in asthma." (PMID 23634778, 2013).